ZFHX3 (zinc finger homeobox 3)
Diseases named in the same sentence as ZFHX3 in open-access papers (continued):
Sharing a sentence is not in itself a finding about the gene and the disease.
tumor (59 papers, 2008 to 2025). "The number of residual tumor cells in the ZFHX3 mutation group was significantly lower than that in the ZFHX3-WT group (P < 0.05)." (PMID 39723215, 2024). "The risk allele of rs8052683, located at the intronic region of ZFHX3 which has a tumor suppressive role in PrCa30, was found to be the same association direction across ancestries and showed associations with reduced expression in the prostate." (PMID 37612283, 2023). "ZFHX3 is a putative tumor suppressor gene and has been frequently found mutated in solid cancers." (PMID 37749078, 2023). "A somatic missense mutation p.Y1545C of unknown significance in ZFHX3 (Zinc Finger Homeobox 3), a transcription factor regulating neuronal differentiation with tumor suppressor role, was found only in the temporal tumor." (PMID 32014051, 2020). "Differential expression analysis and ceRNA network analysis showed several tumor-associated transcripts (Dock4, Fmr1, Zfhx3, Ralb, Mll, Aoc3, and circHRH4) may involve in ALV-J-induced tumorigenesis." (PMID 30286182, 2018). "Our data also suggest that CSK low CRPCs might respond to inhibition of pathways and cellular processes set into motion by loss of ETS2 and ZFHX3 function, two tumor suppressors specifically involved in the transition to CRPC, although regimens to do so remain to be discovered." (PMID 26091350, 2015). "At low IIS, we find that the zinc finger and homeobox protein ZFH-2, the worm ortholog of the ZFHX3 tumor suppressor, forms a complex with DAF-16 in the nucleus and, like DAF-16, extends lifespan." (PMID 41381452, 2025). "Seven heterozygous protein-truncating mutations were found in tumor suppressor genes including RB1, FBXO11, FAT1, KMT2D, KMD6A, ACVR2A and ZFHX3." (PMID 36702998, 2023). "ZFHX3, namely zinc finger homeobox 3, is an inhibitor of alpha-fetoprotein gene and one of the tumor suppressor genes in many cancers." (PMID 37261523, 2023). "ATBF1, encoded by ZFHX3, negatively regulates AFP and MYB, positively regulates CDKN1A expression, and has been reported as a tumour suppressor gene in other types of cancer." (PMID 38104198, 2023). "The heatmap demonstrated that tumours with a higher ZFHX3 level also had a higher AR activity (left)." (PMID 34953044, 2022). "The zinc-finger homeobox 3 (ZFHX3) is a tumor suppressor gene and knockout of ZFHX3 in mouse leads to development of neoplastic lesions." (PMID 35831290, 2022). "ZFHX3 (zinc finger homeobox 3) is essential for regulating myogenic and neuronal differentiation, and it was reported to function as a tumor suppressor in several cancers." (PMID 34107880, 2021). "Previous reports have shown that the tumour suppressor isoform of ZFHX3 (isoform P1) upregulates the expression of the tumour suppressor CDKN1A and downregulates the expression of the oncogene MYB." (PMID 33499898, 2021). "Opposite to what we expected from a TSG, we found that 50% (8/16) of GC tumours had upregulated H3K4me3 on the ZFHX3 promoter." (PMID 33499898, 2021). "Similar to what we observed in cultured cell lines, CRISPR-mediated suppression of CIT or ZFHX3 led to the reduction in expression of the target and tumour size." (PMID 33499898, 2021). "ZFHX3, Zinc Finger Homeobox 3, was first identified as a suppressor of alpha-fetoprotein gene and is a tumor suppressor in several cancers." (PMID 33479213, 2021). "Specifically, we find that the tumour suppressor ZFHX3 expresses an isoform that has a paradoxical oncogenic role that correlates with poor patient outcome." (PMID 33499898, 2021). "ZFHX3 overexpression in T-47D cells significantly increased tumor volume, tumor weight, and the Ki67 proliferation index when compared with control groups." (PMID 33217982, 2020). "More directly, SUMOylation of ZFHX3 at lysine 2806 is essential for its tumor-promoting effect on the tumorigenicity of MDA-MB-231 cells, as the mutation of lysine 2806 in ZFHX3 prevented MDA-MB-231 cells from forming tumors in nude mice." (PMID 33217982, 2020).
tumor (continued). "For the tumor suppressors, there are 3 up-regulated genes (mutations: POLE; CNAs: DNMT3B, RECQL4) and 2 down-regulated genes (CNAs: SDHA; fusions: ZFHX3)." (PMID 32934781, 2020). "Consistently, ZFHX3 silencing in MCF-7 cells significantly decreased tumor growth and cell proliferation." (PMID 33217982, 2020). "In summary, we examined the relationship between two established transcription factors that are not only essential for normal prostate development but are also tumor suppressors in prostatic tumorigenesis, ERβ and ZFHX3." (PMID 30979864, 2019). "Considering that ZFHX3 is necessary for ERβ to repress MYC transcription, it is reasonable to propose that ERβ also depends on ZFHX3 to exert its tumor suppressor activity." (PMID 30979864, 2019). "Our findings in this study have established ZFHX3 as an indispensable factor for the tumor suppressor activity of ERβ." (PMID 30979864, 2019). "This provides the first evidence that CTCF inactivation in conjunction with inactivation of CDH1 and/or ZFHX3 and/or other candidate genes on 16q contributes to the development of poorer prognosis tumour subtypes." (PMID 28319062, 2017). "The cell cycle arrest and neuronal differentiation marker ZFHX3 was identified as one of PRC2-silenced tumor suppressor candidates." (PMID 28984200, 2017). "Blocking PRC2 reduced tumor cell growth and increased the mRNA expression levels of ZFHX3 in an early treatment stage." (PMID 28984200, 2017). "We propose ZFHX3 to be a new tumor suppressor candidate in HR-NB, which is worth further investigation." (PMID 28984200, 2017). "Moreover, the tumour sample T10 was the only sample that presented three potential driver mutations: BRAF, ZFHX3 and telomerase reverse transcriptase (TERT) promoter." (PMID 37317665, 2023). "It has been reported that the inactivation of ZFHX3 may correlate with tumor aggressiveness, especially in subjects with the deletion of chromosome 16q that contains this gene." (PMID 35347810, 2022). "Molecularly, MYC and TBX3 could be partially responsible for ZFHX3′s promoting cell proliferation and tumor growth effects." (PMID 33217982, 2020). "In addition, inactivation or deletion of CCCTC-binding factor (CTCF) and zinc finger homeobox 3 gene (ZFHX3), encoded by tumor suppressor genes on chromosome 16q22 can also affect the occurrence of EC." (PMID 32412912, 2020). "ZFHX3 is also a transcription factor, it acts as a tumor suppressor in multiple cancer types." (PMID 31053132, 2019). "Residing on 16q are many notable tumor suppressor genes including LC3B, CYLD, CDH11, CDH1, ZFHX3, CREB, CTCP, and all metallothioneins (MTs), which emerging research indicates are also tumor suppressors." (PMID 40565600, 2025). "Copy losses were also commonly observed for key tumor suppressors relevant to mCRPC biology, including GRHL2, ZFHX3, FGFR2, NCOR1, PHLPP1, and BRCA1." (PMID 31136607, 2019). "In the BRCA tumor sample, a region of the anti-sense strand of gene MYLK3 is inserted after the third exon of the ZFHX3 gene." (PMID 29650026, 2018).
tumor (continued). "In case 2, we observed all 5 tumor samples and non-tumor samples had mutations in many of the same genes such as AHNAK2, ZFHX3, KMT2C and MAP3K1." (PMID 41471728, 2025). "Pearson correlation analysis further confirmed the positive correlation between ZFHX3 expression levels and AR activity scores regardless of tumour stage, grade, metastasis or age (data not shown)." (PMID 34953044, 2022). "Five of the genes affected by a single technology indel (WGS) in the MSI tumor (GNAS, HOXC13, MAPK1, and ZFHX3) and two of the genes affected by a single technology indel (WGS) in the MSS tumor (GNAS and HOXD13) were also listed in the cancer gene census list of the COSMIC database." (PMID 28683819, 2017). "Although MYC and TBX3 could partially mediate ZFHX3′s promoting effects on cell proliferation and tumor growth, direct evidence is still lacking at this time because findings from the rescue experiments were not conclusive." (PMID 33217982, 2020). "Molecularly, ZFHX3 could bind to the promoters of MYC and TBX3 to activate their transcription, which could then partially mediate ZFHX3′s effects on cell proliferation and tumor growth." (PMID 33217982, 2020).
cancer (42 papers, 2008 to 2026). A tumor composed of atypical neoplastic, often pleomorphic cells that invade other tissues. "SOX5, KANK1, and ZFHX3 are transcription factors implicated in specific cancer entities and regulate cell development, migration, and genomic stability." (PMID 40456839, 2025). "ZFHX3 encodes Zinc Finger Homeobox 3 (AT Motif-Binding Factor 1) and has been implicated in promotion and suppression of cancers, in regulating neuronal differentiation, and in regulating circadian function in the Suprachiasmatic Nucleus." (PMID 38201209, 2023). "ZFHX3 is known as a tumour-suppressor gene (TSG) that is frequently mutated in various cancer types." (PMID 33499898, 2021). "Patients with copy number gains in KLF5 and ZFHX3 were at a 3.2-fold and 2.5-fold increased risk of cancer-specific mortality, respectively." (PMID 28915599, 2017). "In univariable logistic regression analysis, copy number gains in KLF5 (hazard ratio (HR): 3.2; 95% confidence interval (CI): 1.2–9.1; p = 0.025) and ZFHX3 (HR: 2.5; 95%CI: 1.1–6.0; p = 0.038) were associated with cancer-specific mortality." (PMID 28915599, 2017). "Thus, late acquisition of ZFHX3 mutations is associated with better prognosis in at least two different cancers, i.e., NSCLC and PCa." (PMID 37749078, 2023). "Our study additionally identified a similar role for EPHA7 and ZFHX3 mutations in NSCLC, consistent with prior observations from a large pan-cancer cohort." (PMID 35798829, 2022). "Since PTEN and ZFHX3 were described as TSGs for many cancers, we wanted to evaluate the level of transformation that these genetic alterations provide to untransformed MCF10A cells." (PMID 36613756, 2022). "Among cancer-related genes, CARD11(18%) and IRS1(18%) were the most common somatic mutated genes, followed by PSMD11, RELN, RRAS2, SMC1A, SYNE1 and ZFHX3, and the mutation rates of the latter six genes were all 14%." (PMID 36457486, 2022). "Hence when mutated, ZFHX3 may influence the occurrence of cancer." (PMID 33933102, 2021). "It was uncovered that PTEN, ARID1A, PIK3R1 and ZFHX3 were important suppressors that participated in cancer development." (PMID 32699528, 2020). "Two HIOTs of RGN11153 are found in cancer genes ZFHX3 (exon) and SOHLH2 (intron)." (PMID 35831290, 2022). "Thus, we have identified two types of transcripts: (a) transcripts that are not expressed in normal conditions and are gained in cancer (e.g. CIT, CCNE1) and (b) transcripts that gain an additional cancer-associated transcript (e.g. MTA3, ZFHX3)." (PMID 33499898, 2021). "The two cancer-related genes, pre-mRNA processing factor 40 homolog B (PRPF40B) and zinc finger homeobox 3 (ZFHX3), were suggested to be potential target mRNAs of lncRNA AC079228.1." (PMID 36819921, 2023). "Zfhx3 and Notch3 in the HIF-related cancer signal pathway were upregulated under hypoxia, while phosphatase, tensin (Pten), and receptor tyrosine-protein kinase (Errb2) were downregulated after continuous hypoxia." (PMID 36147561, 2022). "ZFHX3 is a transcription factor and negative regulator of c-Myb that has been previously reported as gained in canine OS, and has been shown to be altered in a mutually exclusive manner with MYC in human cancers." (PMID 40493617, 2025). "Both ZFHX3 and BAP1 are tumor suppressor genes, their decreased expression may promote the cancer development." (PMID 30107644, 2018). "Patients with CNV in KLF5, ZFHX3 and CDH1 had reduced cancer-specific survival, compared to patients without CNV in these genes (pairwise p = 0.028, 0.026, 0.044, respectively)." (PMID 28915599, 2017). "However, patients with copy number gains in KLF5, ZFHX3 and CDH1 had reduced cancer-specific survival, compared to patients without CNV in these genes ZFHX3 and CDH1, respectively (pairwise p ≤ 0.044)." (PMID 28915599, 2017). "However, patients with CNV in specific genes, such as ZFHX3, KLF5 and CDH1, had reduced cancer-specific survival compared to patients without CNV in these genes." (PMID 28915599, 2017).
cardiovascular disease (3 papers, 2014 to 2025). "The chromosome 16q22.3 region contains the locus encoding the zinc-finger homeobox protein ZFHX3 and has been shown to be associated with susceptibility to several cardiovascular disease phenotypes." (PMID 25539802, 2014). "Variants associated with cardiovascular disease span a region of 43 kb within the first intron of ZFHX3." (PMID 25539802, 2014).
infection (2 papers, 2018 to 2024). The state of being infected such as from the introduction of a foreign agent such as serum, vaccine, antigenic substance or organism. "As previously reported in WT mice, Zfhx3+/+ mice breathing 10% CO2 experienced greater histologic lung injury than air-breathing mice following infection with IAV at both 30 and 3 pfu per animal." (PMID 38227369, 2024). "The up-regulated TF ZFHX3 targets seven genes in module AD_M25, where two genes OAS1 and RSAD2 are detected in infection pathways, and the other five genes FAM122B, SAMD9, TRIM21, USP18 and IFIT3 are also known to be related to infectious disease." (PMID 30598117, 2018).
bacterial infection (1 paper, 2024). "We chose to investigate the role of Zfhx3 as a potential mediator of CO2 effects on the immune system in mice because of its homology to Drosophila zfh2, which we previously identified as a mediator of CO2-induced suppression of host defense against bacterial infection in the fly." (PMID 38227369, 2024).
heart disease (1 paper, 2013). "Six candidate genes including LMNA, Zinc Finger Homeobox 3 (ZFHX3), Matrix Metallopeptidase 2 (MMP2), Angiopoietin-Like 5 (ANGPTL5), Myosin Heavy Chain 7B (MYH7B) and Potassium voltage-gated channel subfamily H member 6 (KCNH6) have been previously linked to heart disease." (PMID 24349489, 2013).
infectious disease (1 paper, 2018). A disorder directly resulting from the presence and activity of a microbial, viral, or parasitic agent in humans. "What caught our interest is the transcription factor ZFHX3 that targets AD-specific module AD_M25 which are associated with infectious diseases from our enrichment analysis." (PMID 30598117, 2018). "Transcription factor ZFHX3 was identified as a potential driver regulator targeting the infectious diseases pathways in AD-specific modules." (PMID 30598117, 2018). "In particular, for AD-specific module AD_M25 enriched in infectious disease related pathways, we identified transcription factor ZFHX3 as a potential driver regulator." (PMID 30598117, 2018). "Specifically, we identified ZFHX3 as a key regulator for multiple infectious diseases pathways which are highly enriched in AD-specific modules." (PMID 30598117, 2018). "AD-specific module AD_M25 is regulated by ZFHX3, with target genes in infectious disease pathways." (PMID 30598117, 2018).
neurodevelopmental disorder (1 paper, 2024). A behavioral and cognitive disorder with onset during the developmental period that involves impaired or aberrant development of intellectual, motor, or social functions. "Variants in KIRREL3 and ZFHX3 have recently been associated with ASD and neurodevelopmental disorders, respectively, so it will be interesting to determine how these genes regulate fate of MGE-derived cells in the future." (PMID 38419656, 2024).
ZFHX3 also shares sentences with these, for which no sentence is quoted: bladder cancer (4 papers); glioma (3); breast tumor (2); cervical cancer (2); Kawasaki disease (2); movement disorder (2); ovarian carcinoma (2); polyneuropathy (2); progressive ataxia (2); Sensory neuropathy (2); stomach cancer (2); urothelial bladder carcinoma (2); adenoma (1); alpha-thalassemia/mental retardation syndrome X-linked (1); atrophic gastritis (1); autism (1); autism spectrum disorder (1); autonomic neuropathy (1); autosomal dominant cerebellar ataxia (1); cardiac arrhythmia (1); cerebellar ataxia (1); diabetes mellitus type 2 (1); embryonal carcinoma (1); Esophageal atresia (1); familial atrial fibrillation (1); Friedreich ataxia (1); glioblastoma (1); head and neck squamous cell carcinoma (1); heart failure (1); hereditary cerebellar ataxia (1).
A further 19 diseases each share a sentence with ZFHX3 in 1 paper.